CXCR4 (C-X-C motif chemokine receptor 4)
Diseases named in the same sentence as CXCR4 in open-access papers (continued):
Sharing a sentence is not in itself a finding about the gene and the disease.
WHIM syndrome (continued). "In a mouse model of the WHIM syndrome, which recapitulates the defects observed in human patients, the expression of the mutant forms of CXCR4 in hematopoietic stem cells blocks the release of neutrophils from the bone marrow, inducing apoptosis in neutrophils and eventually neutropenia." (PMID 30233640, 2018). "Unlike other reviews of WHIM syndrome, the remainder of this review will focus on CXCR4 and WHIM mutations in adaptive immunity in patients and in the mouse model of WHIM syndrome." (PMID 30577453, 2018). "Disruption of the CXCR4/CXCL12 balance by inflammatory stimuli can increase neutrophil release into peripheral blood or can lead to leukostasis in the bone marrow such as found in WHIM syndrome." (PMID 30356867, 2018). "For example, if CXCR4 endocytosis was reduced through sequestering of intracellular machinery by US27, this could prevent CXCR4 desensitization and result in increased signal amplitude or more prolonged signaling outcomes, as in WHIM syndrome." (PMID 28207860, 2017). "In addition, the SDF-1/CXCR4 axis plays a critical role in the regulation of the immune system and is involved in the pathogenesis of several immunological conditions, such as WHIM syndrome, rheumatoid arthritis and lupus." (PMID 24505417, 2014). "WHIM syndrome-associated CXCR4 truncation mutants lacking the S346/347 phosphosite and the recently identified E343K WHIM mutant displayed strongly impaired phosphorylation at S324/325 and S338/339 as well as reduced CXCL12-induced receptor internalization." (PMID 23734232, 2013). "To test this hypothesis, we generated novel phospho-selective CXCR4 antibodies and examined site-specific phosphorylation at S324/325, S338/339, and S346/347 in CXCR4 wildtype and WHIM syndrome mutant receptors." (PMID 23734232, 2013). "Since previous reports have described reduced ligand-induced CXCR4 internalization in cells from patients with WHIM syndrome, we tested whether HeLa cells expressing the WHIM-associated CXCR4 mutant show a similar impairment." (PMID 19956569, 2009). "Interestingly, the gain of function mutation in CXCR4 causing WHIM syndrome allows remyelination to take place, even in the absence of testosterone, but its potentiating effects remained observable." (PMID 38291527, 2024). "Thus, CXCR4 genetic is a crucial hub for the pathogenesis of both WHIM syndrome and WM, and deciphering the aberrant signaling profile represents a fundamental element for the identification of relevant biomarkers and the development of precision therapy in both diseases." (PMID 32784523, 2020). "Interestingly, a detailed study of two unrelated patients with a full clinical form of WHIM syndrome but lacking detectable mutations in CXCR4 showed hyperactive responses to CXCL12." (PMID 32784523, 2020). "Additionally, WHIM syndrome (Warts, Hypogammaglobulinemia, Infection, and Myelokathexis) is the only known immunological disease directly results from aberrant CXCR4 function, and it has been attributed to a deletion of C-terminal residues of CXCR4 that prevents proper receptor internalization." (PMID 31139626, 2019). "Burixaofr is also known to block CXCR4 and lower CXCL12 driven trafficking, with clinical trials underway for modulating inflammation in WHIM syndrome." (PMID 41256885, 2025). "It has been demonstrated in patients with WHIM syndrome that GRK6 and β-arrestin-2 recruitment is impaired, leading to the gain-of-function CXCR4 activity responsible for the abnormal cellular trafficking of the receptor." (PMID 36883568, 2023). "To better understand the properties of S339fs5 compared with WT CXCR4 and other WHIM syndrome mutants such as R334X, we established HEK293 cell lines stably expressing WT or mutant CXCR4." (PMID 34973340, 2022).
WHIM syndrome (continued). "In 2008, the FDA approved the first CXCR4 antagonist, plerixafor (AMD3100), for the mobilization of hematopoietic stem cells, and several other CXCR4 antagonists are currently in clinical trials for the treatment of cancer, HIV, and WHIM syndrome." (PMID 24505417, 2014). "Alternatively, preclinical studies in animal models of WHIM syndrome may be used to provide insights into potential WHIM pathogenesis in tissues and the impact of CXCR4 antagonism on these processes." (PMID 39588369, 2024). "However, a comprehensive side-by-side characterization of CXCR4 variants, to delineate whether potential functional differences of the individual CXCR4 mutations could explain the variable phenotypic presentation of patients with WHIM syndrome, was lacking." (PMID 36089616, 2022). "Early studies that have identified the role of CXCL12/CXCR4 in human immunodeficiency virus (HIV) pathogenesis, later in cancer progression and metastasis and more recently in the pathogenesis of WHIM syndrome have facilitated research devoted to the regulation of this signalling axis." (PMID 33466410, 2021). "Moreover, several other CXCR4 antagonists are currently in clinical trials for cancer, HIV and WHIM syndrome treatment, highly supporting its potential use for the treatment of CPSP in clinic." (PMID 28785202, 2017). "When deregulated, as in the WHIM syndrome, the CXCL12/CXCR4 pathway can trigger HPV-induced transformation as a result of elevated levels of oncoprotein-induced signaling and down-regulation of DNA damage response pathways associated with cell hyperproliferation." (PMID 27918748, 2016). "Recently, a patient with WHIM syndrome who did not have a mutant CXCR4 (WHIM WT) was reported to have a selective decrease in GRK3 expression levels." (PMID 19956569, 2009). "Plerixafor (AMD3100, Mozobil; Sanofi-Genzyme) is a CXCR4 antagonist that rapidly, transiently, and nonselectively increases levels of most circulating leukocytes in both healthy individuals and patients with WHIM syndrome." (PMID 37561579, 2023). "A mouse model of WHIM syndrome generated by Balabanian and colleagues reproduced several hematological defects seen in WHIM patients, including peripheral blood leukopenia, that could be reversed by CXCR4 antagonism." (PMID 33324418, 2020). "The orally bioavailable CXCR4-selective antagonist, X4P-001 (X4-Pharma) has been reported to be well-tolerated and able to increase the ANC and ALC (which increased in greater proportion than the ANC) in a dose-dependent manner during a phase II trial consisting of four WHIM syndrome patients." (PMID 30577453, 2018). "Failure to internalize the CXCR4 receptor prevents downregulation of CXCR4-mediated signalling and is responsible for the retention of neutrophils in the bone marrow or caudal hematopoietic tissue of WHIM syndrome patients and a zebrafish model of WHIM syndrome, respectively." (PMID 22844288, 2012). "Since CXCR4 signaling is induced by different ligands and affects important biological processes, it is not surprising that CXCR4 is also involved in a plethora of pathological events, such as HIV infection, WHIM syndrome, as well as diverse cancer types." (PMID 26347749, 2015).
breast tumor (89 papers, 2005 to 2025). "We then focused our efforts on the regulation of the metastasis-related CXCR4 gene because it is associated with stem cell acquisition and aggressive growth of breast tumors." (PMID 30486409, 2018). "In fact, patients with breast tumors showing CXCR4 overexpressing were associated with an increased number of metastases in lymph nodes and a decreased overall survival comparing to tumors with low CXCR4 expression." (PMID 30012106, 2018). "In this context, the aim of this study was to investigate the influence of CXCR4 rs2228014 genetic polymorphism on its gene and protein expression in breast tumor samples." (PMID 26576337, 2015). "Another study suggests that CXCR4 expression in the primary breast tumor is associated with a higher risk for bone metastasis." (PMID 25237365, 2014). "Increased expression of CXCR4 in primary breast tumors has been associated with developing bone metastases." (PMID 22053985, 2011). "Aberrant CXCR4 overexpression has been implicated in breast tumor growth and metastasis." (PMID 26993780, 2016). "It is a very effective and particular chemokine receptor CXCR4 antagonist that suppresses tumor development and proliferation while also boosting the immune system within the microenvironment of breast tumors." (PMID 40584290, 2025). "The conjugation of RENPs with a CXCR4 targeted drug enables precise delineation of breast tumors using a near‐infrared imaging system and improves radiation efficacy via lutetium‐based radio‐sensitizer in vivo." (PMID 38774946, 2024). "We next investigated the biorecognition of sequentially delivered Nanothread-1 and Nanothread-2 in mice bearing orthotopic 4T1 breast tumors overexpressing CXCR4." (PMID 38553476, 2024). "CXCR4 was found on the surface of murine breast tumour 4T1 BC cells, and it was found to increase breast tumour development and metastasis when combined with the chemokine CXCL12 (SDF-1)." (PMID 37162544, 2023). "For example, Mueller and co-workers reported that the CXCL12/CXCR4 axis plays a central role in regulating metastasis by showing that normal breast tissues express little CXCR4 receptors compared to breast neoplasms, which express high levels of CXCR4." (PMID 36826044, 2023). "CCR3 and CX3CR1 were differentially expressed between Black versus White, and CCR6, CCRL2, and CXCR4 between Asian versus White breast tumors." (PMID 35754051, 2022). "Additional findings connected chemokines with CSCs and resistance to therapy by demonstrating that CXCR4 signaling was required for the generation of cells with CSC characteristics out of tamoxifen-resistant luminal-A breast tumor cells." (PMID 32582148, 2020). "Upon intravenous administration, this virus blocked CXCL12/CXCR4 signaling, inhibiting the recruitment of circulating endothelial progenitors (CEPs) into the stroma and destructing the tumor vasculature in human breast tumor bearing mice." (PMID 33167307, 2020). "Roles for CXCR4 in resistance to endocrine treatments were also demonstrated when CXCL12 administration has increased the volumes of tumors generated by luminal-A breast tumor cells in mice treated by the estrogen receptor antagonist Fulvestrant." (PMID 32582148, 2020). "Additional research in this direction provided evidence to complex roles for CXCR7/ACKR3 and for its interactions with CXCR4 in regulating the proliferation and growth of breast tumor cells." (PMID 32582148, 2020). "Several preclinical studies targeting the CXCR4/CXCL12 axis have been recently conducted in breast tumors." (PMID 30012106, 2018). "Accordingly, a strong expression of CXCR4 has been demonstrated in primary breast tumors, axillary LN metastases, and distant metastases of the lung and liver." (PMID 29849822, 2018). "In particular, Cxcl12 expression was strongly enhanced in interleukin 7-producing fibroblasts and cell type-specific genetic ablation and systemic pharmacological inhibition revealed that the CXCL12/CXCR4 axis impacts breast tumor cell stemness." (PMID 29632733, 2018).
breast tumor (continued). "The apparent reduced angiogenic proteins (CD34 and Factor VIII) expressions and down-regulated metastasis-related VEGFR1 and CXCR4 gene expressions were observed in breast tumors." (PMID 27731376, 2016). "The expression of CXCR4/SDF-1 in breast tumours has been correlated with a poor prognosis, increased metastasis." (PMID 25753200, 2015). "It was revealed that breast neoplasms expressed high levels of CXCR4, whereas healthy breast tissues expressed low levels." (PMID 26622806, 2015). "In vitro experiments revealed that MB231/miANGPTL2 attenuates breast tumor cell responsiveness to CXCL12 stimulation by decreasing CXCR4 expression in those cells." (PMID 25773070, 2015). "The main goal of the study is the contribution of exosomes released from CXCR4-breast tumor cells to tumor growth, dissemination capacity and generation of stem cell features after uptake by recipient cells." (PMID 26528758, 2015). "A recent study also showed that CXCR7-positive tumor cells promoted the metastasis of CXCR4-positive breast tumor cells." (PMID 25884570, 2015). "Inhibition of CXCR4 expression by TPD7 further correlated with the suppression of SDF-1α-induced migration and invasion in breast tumour cells, knockdown of CXCR4 attenuated TPD7-inhibitory effects." (PMID 25753200, 2015). "In summary, this study demonstrates how exosomes derived from CXCR4-breast tumor cells modify stemness markers and enhance proliferation, migration and invasion abilities of neighboring cells." (PMID 26528758, 2015). "The expression of CXCR4 mRNA was investigated by qPCR in breast tumor tissue and in normal mammary gland." (PMID 26576337, 2015). "Here we analyzed the exosomes release by breast tumor cells with different capacities of stemness/metastasis based on CXCR4 expression, and evaluated their capacity to generate oncogenic features in recipient cells." (PMID 26528758, 2015). "There is little experimental data demonstrating CXCR4 expression status in different breast tumor microenvironments, considering the mediators of inflammation related to cancer." (PMID 26161302, 2015). "Initially, the authors suggested that the majority of breast tumors have cells with different CXCR4 expression levels, and this was directly related to the metastatic potential." (PMID 26161302, 2015). "As well as a mediator of metastasis, CXCR4 signalling has been found to contribute to breast tumour growth at the primary site; however its function in stem cell activity, both normal and malignant, has not yet been investigated." (PMID 24583601, 2014). "AMD4365, a novel derivative acting as CXCR4 antagonist inhibits breast tumor formation and reduces lung and liver metastasis acting both on tumor and immune cells present in the tumor microenvironment." (PMID 24904289, 2014). "CTCE-9908 inhibits human breast tumor cells growth in mouse xenografts impairing the CXCR4–VEGF loop and lowering tumor VEGF levels and affects breast, prostate and esophageal cancer metastasization in murine models." (PMID 24904289, 2014). "This suggests that metastatic breast tumor cells selectively express CXCR4 which leads them to organs with high expression levels of CXCL12." (PMID 24259307, 2013). "Our data suggest that BD specifically targets expression of PLAU and CXCR4 in triple-negative and highly aggressive breast tumors in vivo." (PMID 22842551, 2012). "To evaluate the effect of BD on the expression of PLAU (uPA protein) and CXCR4 genes in breast tumors, we isolated RNA and performed quantitative RT-PCR in control and BD treated mice as described in Materials and methods." (PMID 22842551, 2012). "In agreement with our in vitro study, BD treatment significantly downregulated expression of PLAU (p=0.026) and CXCR4 (p=0.002) in breast tumors." (PMID 22842551, 2012). "This study provides novel insights into the crosstalk between CB2 and CXCR4/CXCL12-signaling pathways in the modulation of breast tumor growth and metastasis." (PMID 21915267, 2011).
breast tumor (continued). "In summary our data demonstrate for the first time that CXCR4 gene expression in primary breast tumors is regulated by DNA methylation, and CXCR4 methylation associates with several clinicopathological parameters." (PMID 22220212, 2011). "Targeting CXCR4 with neutralizing antibodies and small molecule antagonists has been shown to inhibit breast tumor growth and metastasis in vitro and in vivo." (PMID 21915267, 2011). "In this study, we investigated the methylation status of the 5′ TSS region of the CXCR4 promoter in primary breast tumor samples." (PMID 22220212, 2011). "The CXCR4 gene is upregulated in several types of cancers, including skin, lung, pancreas, brain and breast tumors." (PMID 22220212, 2011). "The MSP assay was subsequently used to analyze the methylation of the CXCR4 gene in primary breast tumor samples." (PMID 22220212, 2011). "In our work, we therefore selected the TSS region, comprised of nucleotides from the positions −173 to +11 in the CXCR4 promoter, to analyze in our breast tumor cell lines and tumor samples." (PMID 22220212, 2011). "In this study, we evaluated the methylation pattern of the CXCR4 gene promoter in breast tumor cell lines and primary tumor samples and correlated this pattern with clinicopathological data." (PMID 22220212, 2011). "Immunhistochemistry studies of primary breast tumours have also demonstrated a relationship between CXCR4 expression and metastases." (PMID 20492653, 2010). "These in vivo findings are corroborated by the observation that CXCR4 is upregulated in HER2/neu overexpressing primary breast tumour tissues and is correlated with poor patient survival." (PMID 17245339, 2007). "We found the median expression of CXCR4 to be significantly higher in breast tumours, in both primary and metastatic carcinomas, than in normal mammary tissue (P=0.0027 and 0.016, respectively)." (PMID 16189523, 2005). "Analysis of patient-derived samples and public databases revealed a significant upregulation of DEC1 and CXCR4 in breast tumors compared with adjacent normal tissues, with elevated levels correlating with increased metastatic potential, suggesting their synergistic involvement in BC progression." (PMID 40420604, 2025). "Also, a discrepancy has been reported between diffuse cytoplasmatic CXCR4 in 81% compared to membrane-localized CXCR4 in only 25% of breast tumors using immunohistochemistry staining." (PMID 40075611, 2025). "However, their role in modulating CXCR4 and subsequent downstream genes that affect the CXCR4/miRNA-transfected breast tumor cell phenotype has been rarely investigated." (PMID 34070538, 2021). "HER2-mediated CXCR4 expression can enhance breast tumor cell invasion and lung metastasis." (PMID 34070538, 2021). "IL1B, IL6, TNF, IL8 and CXCR4 mRNA levels were significantly increased in the high AHR-expressing ERα-negative breast tumor subpopulation, while these associations were only observed for IL6 and CSF1 in the ERα-positive tumor subgroup." (PMID 29320557, 2018). "Moreover, immunofluorescence and flow cytometry analysis of orthotopic primary breast tumors also presented a remarkably higher expression level of CXCR4, in contrast to lung metastatic lesions." (PMID 30012106, 2018). "Primary breast tumors express CXCR4, one of the metastasis markers, and secrete PTHrP." (PMID 30151009, 2018). "Moreover, CXCR4-targeted tracer accumulation in the breast tumors varied significantly between patients." (PMID 30191351, 2018). "Indeed, breast tumor aggressiveness has been associated with increased COUP-TFI expression, decreased CXCL12 and CXCR7 expression, and increased CXCR4 expression." (PMID 28666461, 2017). "CXCR4 mRNA level was positively correlated with BAG3 mRNA expression in breast tumor tissues." (PMID 28703799, 2017). "Thus, we focused on the molecular mechanism by which PPARγ mediates the inhibition of CXCR4 expression in breast tumor cells." (PMID 27556298, 2016).